EIF3D (eukaryotic translation initiation factor 3 subunit D)
Description:
mRNA cap-binding component of the eukaryotic translation initiation factor 3 (eIF-3) complex, a complex required for several steps in the initiation of protein synthesis of a specialized repertoire of mRNAs. The eIF-3 complex associates with the 40S ribosome and facilitates the recruitment of eIF-1, eIF-1A, eIF-2:GTP:methionyl-tRNAi and eIF-5 to form the 43S pre-initiation complex (43S PIC). The eIF-3 complex stimulates mRNA recruitment to the 43S PIC and scanning of the mRNA for AUG recognition. The eIF-3 complex is also required for disassembly and recycling of post-termination ribosomal complexes and subsequently prevents premature joining of the 40S and 60S ribosomal subunits prior to initiation. The eIF-3 complex specifically targets and initiates translation of a subset of mRNAs involved in cell proliferation, including cell cycling, differentiation and apoptosis, and uses different modes of RNA stem-loop binding to exert either translational activation or repression. In the eIF-3 complex, EIF3D specifically recognizes and binds the 7-methylguanosine cap of a subset of mRNAs. (Microbial infection) In case of FCV infection, plays a role in the ribosomal termination-reinitiation event leading to the translation of VP2.
Synonyms: EIF3S7; eIF3-p66; eIF3-zeta
Tractability: Small molecule: a structure with a bound ligand is known. PROTAC: ubiquitination databases record sites on it; its protein half-life has been measured.
Gene: Protein-coding gene on chromosome 22 (36,510,850 to 36,529,245, reverse strand). Ensembl gene ENSG00000100353.
Subcellular location: Cytoplasm
Subcellular location (Human Protein Atlas): Cytosol
Pathways (Reactome):
Metabolism of proteins: Formation of a pool of free 40S subunits; Formation of the ternary complex, and subsequently, the 43S complex; GTP hydrolysis and joining of the 60S ribosomal subunit; L13a-mediated translational silencing of Ceruloplasmin expression; Ribosomal scanning and start codon recognition; Translation initiation complex formation
Gene Ontology:
Molecular function: mRNA cap binding; protein binding; RNA binding; translation initiation factor activity
Biological process: cap-dependent translational initiation; formation of cytoplasmic translation initiation complex; IRES-dependent viral translational initiation; translational initiation; viral translational termination-reinitiation; cytoplasmic translational initiation
Cellular component: cytosol; eukaryotic translation initiation factor 3 complex; membrane; cytoplasm; eukaryotic 43S preinitiation complex; eukaryotic 48S preinitiation complex; eukaryotic translation initiation factor 3 complex, eIF3m; synapse
Genetic constraint (gnomAD): Loss-of-function variants: 8 observed, 75.38 expected, observed/expected ratio (o/e) 0.11, 90% interval 0.061 to 0.19. The upper end of that interval is the gene's LOEUF score, 0.19, which puts it in group 1 of 6, group 1 being the genes least tolerant of losing a copy. Missense variants: 387 observed, 727.78 expected, observed/expected ratio (o/e) 0.53, 90% interval 0.49 to 0.58. Synonymous variants: 243 observed, 257.73 expected, observed/expected ratio (o/e) 0.94, 90% interval 0.85 to 1.05.
Homologues: Orthologues: chimpanzee EIF3D (100% identical), macaque EIF3D (100% identical), pig EIF3D (99% identical), mouse Eif3d (99% identical), rat Eif3d (99% identical), guinea pig EIF3D (99% identical), rabbit EIF3D (99% identical), dog EIF3D (99% identical), zebrafish eif3d (91% identical), tropical clawed frog eif3d (90% identical), Drosophila melanogaster eIF3d1 (57% identical), Drosophila melanogaster eIF3d2 (55% identical), and 1 more.
Diseases named in the same sentence as EIF3D in open-access papers:
EIF3D is named in the same sentence as 52 diseases in open-access papers, as found by Europe PMC text mining. Sharing a sentence is not in itself a finding about the gene and the disease. The quoted sentences say what the papers report.
glioma (13 papers, 2017 to 2023). A benign or malignant brain and spinal cord tumor that arises from glial cells (astrocytes, oligodendrocytes, ependymal cells). "An immunohistochemical study showed that eIF3d is overexpressed in grade-1 and 2 GB brain tumors and U251 and U-87 MG glioma cells, and when eIF3d was knocked out, the cell proliferation and colony formation decreased." (PMID 36994107, 2023). "FLNA was a novel driver gene of tumor metastasis in GBM, and EIF3D was a protective gene for gliomas, of which high expression of EIF3D was related to an improved OS." (PMID 36233273, 2022). "Some studies have shown that the expression of EIF3D is positively correlated with the grade of glioma and the poor prognosis of gastric cancer." (PMID 36003341, 2022). "Overexpression of eIF3C, eIF3D and eIF5A was described in human glioma tissues, predominantly in WHO grades III and IV." (PMID 33807050, 2021). "In both the CGGA and TCGA datasets, the expression levels of eIF3d, eIF3e, eIF3f, eIF3h and eIF3l highly were associated with the IDH mutant status of gliomas." (PMID 31171919, 2019). "Similarly with our findings, EIF3D was found to be up-regulated in recent studies in other cancer types including prostate cancer, non-small cell lung cancer, colon cancer, breast cancer, renal cell carcinomas, melanomas and gliomas." (PMID 29050215, 2017). "However, it has also been observed that eIF3d knockdown using siRNA or shRNA expressed from lentiviral vector reduced cell proliferation, potentially because of arrest at G0/G1 phase with reduction of cells at S or G2/M phase in glioma and gallbladder and breast cancer cells." (PMID 36997088, 2023). "eIF3C, eIF3D, eIF4E and 4E-BP1 correlated with tumour grade with significantly higher levels in HGG compared to LGG (low grade glioma)." (PMID 37907716, 2023). "More studies showed knockdown of EIF3B, decreasing EIF3C, and silencing EIF3D and EIF3E alleviated proliferation and migration of glioma cells." (PMID 32565801, 2020). "Out of the 13 signature genes, ATP6V1E1, EIF3D, ERCC1, GPNMB, MTDH, PCNA and NEDD9 have been reported to play crucial roles in various pathways and mechanism of glioma." (PMID 31632497, 2019). "Regarding the eIF3 complex, significantly higher protein expression in gliomas compared to CCBT was detected for eIF3B (III: p < 0.05), eIF3D (I: p < 0.05; III: p < 0.05), eIF3H (III: p < 0.05), eIF3I (I: p < 0.05, III: p < 0.001, IV: p < 0.01) and eIF3M (III: p < 0.01)." (PMID 33807050, 2021).
breast carcinoma (10 papers, 2017 to 2024). "For example, eIF4E overexpression is frequently found in patients with colorectal cancer (CRC) or breast cancer (BC); eIF5A2 overexpression is obviously associated with the advanced stage of ovarian cancer; eIF3D increases cell cycle progression and motility in prostate cancer (PCa)." (PMID 34016142, 2021). "Previous studies have demonstrated that the downregulation of EIF3D inhibits the growth of non-small cell lung cancer, breast cancer, and kidney cancer." (PMID 38535990, 2024). "In our pan-cancer analysis, significant differential expression of EIF3D was observed in breast cancer (BRCA), bile duct cancer (CHOL), colon and rectal cancer (COAD), and HNSC, with a noteworthy overexpression observed across most tumor types (P < 0.01)." (PMID 38535990, 2024). "The results showed that 17 m7GRGs were risk factors and significantly impacted breast cancer prognosis, whereas NUDT10, NUDT3, EIF4E3, SNUPN, NUDT16, IFIT5 and EIF3D were favourable prognostic factors." (PMID 37353728, 2023). "Consistent with the results of GEPIA and TCGA, it indicated significantly higher EIF3B expression and lower EIF3D/ F/ L in breast cancer tissues." (PMID 35040374, 2022). "EIF3D has also been reported to play some important role in tumors, such as colon cancer, melanoma and breast cancer." (PMID 35602299, 2022). "VCP inhibition by pharmacological compounds or siRNAs induces paraptosis in breast cancer cells by restoring the translation of ATF4 and DDIT4 via eukaryotic translation initiation factor 3 subunit D (eIF3d)." (PMID 39497143, 2024). "Silencing eIF3d in renal cell carcinoma is known to down-regulate the cell cycle B1/cyclin-dependent kinase-1 (CDK1) signalling pathway, and knocking down eIF3d in breast cancer cells inhibits the Wnt/β-catenin signalling pathway." (PMID 31118081, 2019).
prostate carcinoma (9 papers, 2016 to 2025). A carcinoma that arises from epithelial cells of the prostate gland. "It has been shown using immunohistochemical staining and Kaplan–Meier survival analysis that high eIF3d expression is tightly associated with worse prognoses in patients with gastric, gallbladder, lung, and liver cancers, whereas eIF3d expression in prostate cancer associates with better prognosis." (PMID 36997088, 2023). "EIF3D is associated with cell cycle regulation and motility of prostate cancer cells." (PMID 27822437, 2016). "The findings that eIF3d promotes prostate cancer cell proliferation but predicts better prognosis are intriguing but are not entirely unexpected." (PMID 36997088, 2023). "Among a group of m6A readers identified in primary prostate cancer cells using multiomic approach, eIF3d was found to be a good prognosis factor." (PMID 36997088, 2023). "In vitro experiments have shown that the eIF3d gene inhibits prostate cancer progression by regulating translation, the cell cycle, drug response, and multiple signaling pathways at m6A levels." (PMID 36360287, 2022). "EIF3D knockdown suppresses the proliferation of human melanoma cells 18 and prostate cancer cells 19, and similar phenomena have been observed in EIF3D‐knockdown HCT116 colon cancer cells 20, indicating EIF3D's potential role as an oncogene." (PMID 28203520, 2016). "According to molecular evidence, eIF3d may slow the progression of prostate cancer by regulating the translation of proteins involved in multiple signaling pathways, including those associated with the cell cycle and drug responses." (PMID 36360287, 2022). "Multiomics analysis revealed that EIF3D might prohibit the prostate cancer progression through translational control of translation, cell cycle, response to drug, and multiple signaling pathways." (PMID 33273988, 2020). "However, in vitro studies showed that EIF3D knockdown suppressed prostate cancer cell proliferation and migration which were modulated by the m6A level." (PMID 33273988, 2020). "Given the prognostic importance of EIF3D and HNRNPA2B1 for both overall and disease-free survival, we investigated their roles in prostate cancer." (PMID 33273988, 2020). "Relevance to clinical features and independent contribution to both overall and disease-free survival highlighted the importance of the translation initiation factor subunit EIF3D and the splicing factor HNRNPA2B1 in prostate cancer." (PMID 33273988, 2020). "The translation initiation factor subunit EIF3D may delay the prostate cancer progression while the splicing factor HNRNPA2B1 may promote prostate cancer progression, in vitro assays proved the roles of EIF3D as well as HNRNPA2B1 in prostate cancer cells." (PMID 34899855, 2021). "Moreover, in vitro assays demonstrated that m6A impacted the EIF3D and HNRNPA2B1 roles in proliferation and migration of prostate cancer cells." (PMID 33273988, 2020). "Furthermore, RNA interference assays of two prognostic m6A readers EIF3D and HNRNPA2B1 were conducted to explore m6A dependence of their functions in prostate cancer cell proliferation and migration." (PMID 33273988, 2020). "Therefore, EIF3I, EIF3D, and HNRNPA2B1 can form a prognostic signature for prostate cancer relapse." (PMID 33273988, 2020). "Furthermore, we revealed the potential cancer-relevant roles of two independent prognostic factors EIF3D and HNRNPA2B1 which may represent promising biomarkers for prostate cancer." (PMID 33273988, 2020).
colon cancer (8 papers, 2014 to 2025). "Similar findings have been made with ectopic eIF3d overexpression in colon cancer cells in which increased cell proliferation was observed as determined using colony formation, MTT, and soft-agar assays." (PMID 36997088, 2023). "Previously published research shows that knockdown of eIF3D suppresses cell proliferation and colony formation via inducing cell-cycle arrest and apoptosis, involving colon cancer and malignant mesothelioma cells." (PMID 35770079, 2022). "Further studies were recently performed, and the lentivirus‐mediated knockdown of EIF3D was found to suppress cell proliferation in human melanoma 18 and colon tumours 20, which indicated a possible role of EIF3D as an oncogene." (PMID 28203520, 2016). "If eIF3D is proved to be the pivotal factor in colon cancer development and progression, then antisense therapy targeting eIF3D will be intriguing." (PMID 25370813, 2014). "At this point, we aimed to examine the effects of eIF3D on colon cancer cell growth via lentivirus-mediated shRNA (short hairpin RNA) in one human colon cancer cell line HCT116." (PMID 25370813, 2014). "eIF3D is essential for colon cancer cell growth, and knockdown of eIF3D resulted in a significant reduction in cell proliferation probably due to activation of AMPKα, Bad, PRAS40, SAPK/JNK and GSK3β, as well as cleavage of PARP." (PMID 25370813, 2014). "Lentivirus-loaded shRNA targeting for eIF3D was constructed to knock down its expression in colon cancer cell line HCT116." (PMID 25370813, 2014). "To further probe into its action in colon cancer, we utilized lentivirus-mediated RNA interference to knock down eIF3D expression in one colon cancer cell line HCT116." (PMID 25370813, 2014). "eIF3d may regulate c-Myc and cyclin D1 expression, which in turn promotes colon cancer cell proliferation." (PMID 36997088, 2023). "Moreover, a series of phosphorylation upregulation was observed along with downregulation of eIF3D in colon cancer cells, including AMPKα, Bad, PRAS409, SAPK/JNK, and GSK3β, as well as the cleavage of PARP." (PMID 31885740, 2019). "Taken together, these findings suggest that eIF3D might play an important role in colon cancer progression." (PMID 25370813, 2014). "Therefore in the present study, we aimed to explore the functional role of eIF3D in colon cancer." (PMID 25370813, 2014). "In the present study, phosphorylation of AMPKα, Bad, PRAS40, SAPK/JNK and GSK3β, as well as cleavage of PARP was elevated in eIF3D knockdown group, adding the evidence that depletion of eIF3D could suppress colon cancer cell growth via the induction of cell-cycle arrest and apoptosis." (PMID 25370813, 2014). "Based on the efficient knockdown, we examined whether the down-regulation of eIF3D influenced the malignant phenotype of HCT116 cells, tending to elucidate its possible role in colon cancer." (PMID 25370813, 2014).
gallbladder cancer (6 papers, 2017 to 2023). "EIF3D was widely studied in cancer and was known to promote the progression of cervical cancer (Zhong and Lan, 2022, 78), gallbladder cancer, and renal cell carcinoma." (PMID 36036011, 2022). "Previous studies have shown that in gallbladder cancer cells, eIF3d leads to tumour progression via stable expression of G-protein coupled receptor kinase 2 (GRK2) and activation of the phosphatidylinositol 3-kinase (PI3K)-AKT signalling pathway." (PMID 31118081, 2019). "Furthermore, immunohistochemical staining showed that GRK2 expression correlated with eIF3d in human gallbladder cancer specimens, consistent with the possible eIF3d regulation of GRK2 expression." (PMID 36997088, 2023). "The over-expression of eIF3D is well-known to promote cell proliferation or/and migration of a variety of advanced gastrointestinal tumor entities, including gastric cancer (GC), and gallbladder cancer (GBC)." (PMID 35770079, 2022). "The overexpression of eIF3D has been observed to promote cell proliferation, migration, or/and tumour growth in several cancer entities, including ovarian cancer, renal cell carcinoma, gastric cancer (GC), and gallbladder cancer (GBC)." (PMID 31885740, 2019). "In this study, we observed that EIF3d levels increased in gallbladder cancer (GBC) samples compared with non-tumor tissue." (PMID 28594409, 2017).
gastric cancer (6 papers, 2014 to 2022). A primary or metastatic malignant neoplasm involving the stomach. "Recently, some studies have found that eIF3D is associated with malignant mesothelioma and gastric cancer, implying its aberrant expression may participate in many pathological processes." (PMID 25370813, 2014). "EIF3D overexpression in lung adenocarcinoma, bladder cancer, and gastric cancer was known as an independent prognostic factor." (PMID 35104170, 2022). "A prospective, high‐throughput transcriptional profiling study was performed to investigate the relationship between EIF3D and different cancers, and the results indicated that EIF3D is up‐regulated in gastric cancer patients resistant to cisplatin and fluorouracil combination chemotherapy." (PMID 28203520, 2016).
melanoma (6 papers, 2016 to 2025). A malignant, usually aggressive tumor composed of atypical, neoplastic melanocytes. "For example, in the eIF3d knockdown study of melanoma cells, it was found that the loss of cell viability might be due to eIF3d knockdown–induced cell cycle arrest at G2/M phase." (PMID 36997088, 2023). "Furthermore, eIF3d silencing using shRNA significantly reduced proliferation of human melanoma cells as determined using methylthiazoletetrazolium (MTT) and colony formation assays." (PMID 36997088, 2023).
renal cell carcinoma (5 papers, 2017 to 2023). "eIF3d knockdown with shRNA reduced, whereas eIF3d overexpression increased sunitinib resistance of the renal cell carcinoma cell lines." (PMID 36997088, 2023). "Mechanistically, eIF3d promoted the sunitinib resistance of renal cell carcinoma partially by blocking the ubiquitin-mediated proteasome degradation of GRP78." (PMID 36997088, 2023).
bladder cancer (4 papers, 2017 to 2022). "eIF3d was shown to be overexpressed in muscle invasive disease and ovarian cancer, whereas the eIF3d knock-down in metastatic T24M bladder cancer cells inhibited cell proliferation, migration, and colony formation in vitro and decreased tumor growth in xenograft models." (PMID 28981723, 2017). "Knock-down of eukaryotic translation initiation factor 3 subunit D (EIF3D) (overexpressed in muscle invasive disease) in metastatic T24M bladder cancer cells inhibited cell proliferation, migration, and colony formation in vitro and decreased tumor growth in xenograft models." (PMID 28880921, 2017). "EIF3D could promote the stability of GRK kinase and activate the Akt signaling pathway, thus promoting the malignant process of bladder cancer." (PMID 35104170, 2022).